KLF4 (KLF transcription factor 4)
Diseases named in the same sentence as KLF4 in open-access papers (continued):
Sharing a sentence is not in itself a finding about the gene and the disease.
gastric cancer (continued). "Stem cell-enriching spheroid culture of the gastric cancer cells increased KLF4 expression and enhanced TRAIL sensitivity with concomitant upregulation of DR4 and DR5." (PMID 36661504, 2022). "Expression of four pluripotency factors (OCT4, Nanog, SOX2, and KLF4) at the transcript level in gastric cancer tissue was analyzed against various pathological parameters using RNASeq data downloaded from the TCGA database." (PMID 36661504, 2022). "The expression of OCT4, SOX2, Nanog, and KLF4 was examined in six gastric cancer cell lines at the basal level and upon a spheroid culture." (PMID 36661504, 2022). "This study aimed to define the role of pluripotency factors (OCT4, SOX2, Nanog, and KLF4) in gastric cancer progression, spheroid forming capacity, and drug resistance." (PMID 36661504, 2022). "Taken together, both results suggest a role of KLF4 expression in the cisplatin response of gastric cancer cells." (PMID 36661504, 2022). "For example, KLF4 was reported to suppress hepatocellular carcinoma progression and inhibit gastric cancer cell proliferation by downregulating β-catenin expression." (PMID 36539799, 2022). "KLF4 expression was lower in the late and advanced stage of gastric cancer and its expression was inversely correlated with patients’ prognosis." (PMID 36661504, 2022). "Overall, pluripotency factor expression was divergent in the gastric cancer cell lines as shown in the prominent expression of KLF4 and Nanog in SNU-601 and of SOX2 in SNU-484." (PMID 36661504, 2022). "H. pylori infection results in KLF4 inactivation in gastric carcinoma with a Tet Methylcytosine Dioxygenase 1 (TET1)-independent DNA methylation mechanism." (PMID 35795038, 2022). "Bioinformatics analysis showed that in gastric cancer and rectal adenocarcinoma, the promoter region of KLF4 and KLF5 was significantly hypomethylated." (PMID 34367275, 2021). "Previously, KLF4 has been reported to suppresses expression of Hdc in a gastric cancer cell; we found that it is also involved in differentiation." (PMID 32101568, 2020). "The expression of KLF4 is strongly reduced in gastric cancer samples; furthermore, it is lower in H. pylori-positive tumors in comparison with H. pylori-negative (H. pylori uninfected) tumors." (PMID 33266506, 2020). "Helicobacter pylori infection leads to KLF4 inactivation in gastric cancer through a TET1‐mediated DNA methylation mechanism." (PMID 32017451, 2020). "Induction of gastric cancer by H. pylori infection seems to be mediated, at least in part, by the reduction in KLF4 expression." (PMID 33266506, 2020). "The aim of this study was to explore the new molecular mechanism of KLF4 inactivation in gastric cancer." (PMID 32017451, 2020). "In stomach cancer, lower KLF4 expression is related to patient prognosis and lymph node and distant metastases." (PMID 32017451, 2020). "LncRNA SNHG5 serves as a sponge of miR-32 to promote proliferation and migration of gastric cancer cells via targeting KLF4." (PMID 32351327, 2020). "LncRNA LINC00673 acts as an oncogene in gastric cancer, and it negatively regulates the expression of KLF4." (PMID 33266506, 2020). "The lncRNA SNHG5 is a transcript of small nucleolar RNA host gene 5 that has been reported to suppress gastric cancer cells by competing miR-32 with the mRNA of Kruppel-like factor-4 (KLF-4)." (PMID 31885582, 2019). "In gastric cancer, KLF4 inhibited cell proliferation and metastasis via downregulating β-catenin expression." (PMID 30658712, 2019). "KLF4 inhibition was shown to suppress the cyto-protective autophagy process, which is considered as a source of energy for the anti-apoptotic gastric cancer cells." (PMID 30944375, 2019). "In summary, our study results showed differentially regulated lncRNAs and gastric cancer-associated genes such as EGFR, KLF4, DNMT1 and AGO4 are candidates of ceRNA network in gastric cancer." (PMID 29719612, 2018).
gastric cancer (continued). "This study identifies the gastric cancer-associated genes such as EGFR, KLF4, DNMT1 and AGO4 as candidates of ceRNA network in gastric cancer." (PMID 29719612, 2018). "Another study reveals that miR-103 increases cells proliferation and metastasis through targeting Krüppel-like Factor-4 (KLF4) in gastric cancer." (PMID 29674956, 2018). "The lncRNA SNHG5/miR-32 axis regulates gastric cancer cell proliferation and migration by targeting KLF4, in addition to regulating imatinib resistance in chronic myeloid leukemia via MiR-205-5p." (PMID 30250399, 2018). "The lncRNA SNHG5/miR-32 axis promotes gastric cancer cell proliferation and migration by targeting KLF4." (PMID 29221147, 2017). "In gastric cancer, the role of KLF4 has been featured as a tumor suppressor and acts as a prognosis predictor for survival of patients." (PMID 28938633, 2017). "At the age of 35 to 50 weeks, these Villin-cre-Klf4 knockout mice developed preneoplasia in antrum, and 29% of them progressed to gastric cancer at 80 weeks." (PMID 27713138, 2017). "Overexpression of KLF4 significantly inhibited gastric cancer cell proliferation, invasion and metastatic properties." (PMID 28445396, 2017). "KLF4 has been found to act as a tumor suppressor in GC progression, such as, MiR-32 promotes gastric carcinoma tumorigenesis by targeting Kruppel-like factor 4 and inhibits KLF4 expression in GC cells." (PMID 29221147, 2017). "In fact, KLF4 is a reported target of miR-10b in several contexts such as esophageal cancer, bladder cancer or gastric carcinoma." (PMID 28412746, 2017). "AGS cell proliferation was significantly inhibited by KLF4 expression, further supporting that KLF4 is a tumor suppressor in gastric cancer." (PMID 27277677, 2016). "We analyzed gastric cancer data from The Cancer Genome Atlas (TCGA) database and found that KLF4 was significantly downregulated in tumor samples." (PMID 27277677, 2016). "KLF4 protein was significantly decreased in gastric cancer samples compared with normal gastric mucosa." (PMID 27449096, 2016). "Obvious growth inhibition of SCG7901-Dp71f and SCG7901-Dp71d cells were displayed in our work, which is consistent with the phenotypes of N87 and SK-GT5 gastric cancer cell lines after the restoration of KLF4 expression." (PMID 27449096, 2016). "The KLF4 gene was found to be frequently downregulated in gastric cancers, pancreatic ductal carcinoma, lung cancer, and medulloblastoma." (PMID 24551169, 2014). "In gastric cancer, KLF4 promoter methylation was reported in the −156 to −39 bp region relative to the ATG." (PMID 24551169, 2014). "It has been reported that forced expression of KLF4 in breast tumor cell line and gastric cancer was sufficient to restore E-cadherine expression and inhibit EMT as well as suppressed migration and invasion." (PMID 23418515, 2013). "Disrupted KLF4 expression contributes to Sp1 over-expression, and to the development and progression of human gastric cancer." (PMID 20119532, 2009). "Additionally, some studies suggest that KLF4 overexpression increases the sensitivity of gastric cancer cells to cisplatin and TRAIL, promoting apoptosis through DR4/DR5 upregulation, enhancing cell death induced by these treatments." (PMID 39995670, 2025). "Reduced KLF4 expression is related to poor survival in gastric cancer." (PMID 37833790, 2023). "KLF4 expression was decreased by the treatment of cisplatin or TRAIL in the gastric cancer cells." (PMID 36661504, 2022). "Another study showed that gastric cancer-derived exosomes could promote the M2 polarization of TAMs through the lncRNA HCG18-miR-875-3p-Kruppel-like factor 4 (KLF4) pathway." (PMID 36341377, 2022). "It was speculated that in gastric cancer and rectal adenocarcinoma, abnormal methylation in the promoter region of KLF4 and KLF5 is involved in the progression or suppression of KLF4 and KLF5." (PMID 34367275, 2021). "A study in 2004 showed that KLF4 suppresses expression of Hdc in gastric cancer." (PMID 32101568, 2020).
gastric cancer (continued). "KLF4 plays an important role in the development of gastric cancer induced by Helicobacter pylori." (PMID 33266506, 2020). "In summary, KLF4 acts as a tumor suppressor in gastric cancer." (PMID 33266506, 2020). "In gastric cancer, the expression of KLF4 is regulated by miR-32, miR-103, miR-135b-5p and miR-155." (PMID 33266506, 2020). "In addition to the lncRNAs, we also profiled the expression pattern of identified candidate gastric cancer-associated genes EGFR, FGFR2, KLF4, DNMT1 and AGO4 shortlisted from the analysis of genes by relative quantification." (PMID 29719612, 2018). "KLF4 has been reported to be regulated by miR-10b in gastric carcinoma." (PMID 29375271, 2018). "miR-103 functions as an oncogene by inhibiting its target gene KLF4 in gastric cancer." (PMID 28445396, 2017). "KLF4 was downregulated in gastric cancer, probably by epigenetic regulation." (PMID 27277677, 2016). "Given that 60–80% of intestinal-type gastric carcinomas initiate in the antrum, it is important to determine KLF4 function in this region, especially in the stem cells, which may contribute to both gastric cancer and metaplasia." (PMID 27277677, 2016). "In conclusion, KLF4 is essential for normal homeostasis of antral stem cells; loss of KLF4 and expression of MUC2 could be important markers for gastric cancer diagnosis." (PMID 27277677, 2016). "As KLF4 deletion enhanced gastric cell proliferation, KLF4 may acts as a tumor suppressor in gastric cancer." (PMID 27277677, 2016). "Interestingly, we found that the cell line with the highest level of KLF4 expression (AGS-Akata) is an EBV-superinfected gastric carcinoma line that we previously reported supports unusually high level lytic EBV protein expression." (PMID 26431332, 2015). "Finally, KLF4, an inhibitor of the cell cycle, has been recently found down-regulated in colonic and gastric cancer." (PMID 16919171, 2006). "For example, the expression of KLF4 is decreased in gastric cancer (GC) and typically exerts a tumor‐suppressive role." (PMID 41532367, 2026). "Thus, this study concludes that KLF4 may modulate EMT in gastric cancer cells via the Wnt/β-catenin pathway." (PMID 41883394, 2025). "Furthermore, KLF4 sensitizes gastric cancer cells to cisplatin treatment." (PMID 33266506, 2020). "Based on these results, we hypothesized that KLF4 was a target of miR-103 in gastric cancer." (PMID 28445396, 2017). "In conclusion, our results demonstrated that upregulation of miR-103 might contribute to gastric cancer progression by suppressing KLF4 expression and subsequently promoting the proliferation, migration, and invasion, and inhibiting apoptosis of gastric cancer cells." (PMID 28445396, 2017). "In gastric cancer, exosomes derived from gastric cancer cells carry the long non-coding RNA (lncRNA) HCG18, which reduces the levels of miR-875-3p, thereby increasing KLF4 expression and promoting M2 macrophage polarization." (PMID 39995670, 2025). "For instance, KLF4 upregulates SAMHD1, inhibiting the MAPK/p38 signaling pathway, thereby suppressing the progression of gastric cancer." (PMID 39995670, 2025). "In gastric cancer models, lncRNA HCG18 sponges miR‐875‐3p to relieve its suppression of KLF4, promoting SUMOylated KLF4 to synergize with IL‐4 signaling in activating the PI3K/AKT pathway." (PMID 41360672, 2025). "Taken together, KLF4 is supposed to play a critical role in survival, especially against TRAIL treatment of gastric cancer cells and in gastric cancer progression." (PMID 36661504, 2022). "Changes in the expression of three pluripotency factors (KLF4, Nanog, and SOX2) except OCT4 were examined in the gastric cancer cells treated with cisplatin or TRAIL for 72 h by western blotting." (PMID 36661504, 2022). "Both Nanog and KLF4 altered death receptor expression and TRAIL sensitivity in the gastric cancer cells, however, in the opposite way." (PMID 36661504, 2022).
gastric cancer (continued). "The overexpression of KLF4 and knockdown of Nanog upregulated DR4/DR5 expression and reduced the viability of the gastric cancer cells treated with TRAIL." (PMID 36661504, 2022). "Then, the relationship between KLF4 and KLF5 expression levels and Helicobacter pylori infection in gastric cancer was explored." (PMID 34367275, 2021). "We show here that ΔNp63α inhibits the constitutive activity, as well as KLF4-induced activity, of Zp-driven reporter gene constructs in EBV-negative AGS gastric carcinoma cells." (PMID 34748616, 2021). "Although we found a differential expression of EGFR, FGFR2, KLF4, DNMT1 and AGO4 in gastric cancer samples, only FGFR2 overexpression was statistically significant (P = 0.0449)." (PMID 29719612, 2018). "The prediction identified three microRNAs (miR-21, miR-145 and miR-148a) and five gastric cancer-specific target genes (EGFR, KLF4, DNMT1 and AGO4) which also showed strong correlation with lncRNAs in regression analysis." (PMID 29719612, 2018). "To understand the clinical relevance of these findings, we analyzed the expression of KLF4 and MUC2 in human gastric cancer." (PMID 27277677, 2016). "To test the function of KLF4 in human gastric cancer cells, we infected AGS cell line with adenovirus carrying KLF4, which induces overexpression of KLF4 in the cells." (PMID 27277677, 2016). "The expression of KLF4 and MUC2 was further analyzed in human gastric cancer tissues and adjacent normal tissues." (PMID 27277677, 2016). "KLF4 is thought to function as a tumor suppressor in certain epithelial cell tumors, and its expression is decreased in both EBV-positive NPC and in gastric carcinoma." (PMID 26431332, 2015). "Krüppel-like factor 4 (KLF4) is a potential tumor suppressor in patients with various cancers, including gastric cancer." (PMID 24216700, 2013). "In summary, an association of pluripotency factor expression with clinicopathological parameters of gastric cancer patients and the effect of Nanog and KLF4 expression on the spheroid forming capacity and response to cisplatin and TRAIL treatments of gastric cancer cells are described in this study." (PMID 36661504, 2022). "Therefore, it is necessary to consider the opposite effect of KLF4 and Nanog on the TRAIL response of gastric cancer cells." (PMID 36661504, 2022). "In addition, RA decreased the expression of CSC markers (CD44 and ALDH) and stemness genes (KLF4 and SOX2) and inhibited CSC properties such as tumorspheres formation in gastric cancer." (PMID 34400945, 2021). "KLF4 is a member of the KLF-like factor subfamily of zinc finger proteins, which was recently reported to have a tumor suppressive role in a number of human cancers including bladder cancer, gastric cancer and pancreatic cancer." (PMID 35095494, 2021). "It was revealed that gastric cancer patients infected by Helicobacter pylori had significantly lower KLF4 expression than noninfected patients." (PMID 34367275, 2021). "We analyzed the expression level of gastric cancer-related genes EGFR, FGFR2, KLF4, DNMT1 and AGO4 identified through bioinformatics screening by relative quantification method and observed differential expression of EGFR, FGFR2, KLF4, DNMT1 and AGO4 in tumors." (PMID 29719612, 2018). "As KLF4 deletion induced MUC2 expression in the mouse antrum and KLF4 levels are decreased in human gastric cancer, we analyzed MUC2 expression in a preliminary study using 11 gastric cancer samples provided by NanFang Hospital." (PMID 27277677, 2016).
gastric cancer (continued). "To further examine the correlation between KLF4 and MUC2 in human gastric cancer, and to understand the clinical relevance of these two proteins, we purchased TMA slides composed of 81 tumor samples and 8 normal tissues from the gastric cancer patients." (PMID 27277677, 2016). "The effect of KLF4 and Nanog expression on spheroid formation, and responses to cisplatin and TRAIL treatments, was investigated by either silencing or overexpressing their expression in two gastric cancer cells, SNU-601 (KLF4/Nanog-high) and SNU-638 (KLF4/Nanog-low)." (PMID 36661504, 2022). "However, we did not see any change in MUC2 expression, suggesting that KLF4 does not directly control MUC2 transcription in gastric cancer cells." (PMID 27277677, 2016). "Among the 19 uniquely identified genes, 7 (GSPT1, TFF3, KLF4, ITK, GNB2L1, FLI1, and GNG5) were not included in the KEGG gastric cancer pathway, indicating that they have not been previously recognized as canonical GAC-related genes." (PMID 41284725, 2025).